INS (insulin)
Diseases named in the same sentence as INS in open-access papers (continued):
Sharing a sentence is not in itself a finding about the gene and the disease.
Hypoglycemia (continued). "Insulin autoimmune syndrome (IAS) is a rare cause of hypoglycemia characterized by high levels of blood insulin autoantibodies." (PMID 37587407, 2023). "Mice deficient in Klotho protein show hypoglycemia and high insulin sensitivity, while moderate insulin and IGF-1 resistance was observed in Klotho overexpression." (PMID 38139126, 2023). "Hypoglycemia is especially prevalent in T2D patients treated with oral sulfonylurea agents or exogenous insulin, increasing the susceptibility of this population to cardiovascular events." (PMID 36830610, 2023). "The risk of hypoglycemia is one of the major concerns that limit the usage of insulin both among practitioners as well as patients." (PMID 36650625, 2023). "Multivariate analysis shows the history of previous event(s) of severe hypoglycemia (OR 5.864, p ≤ 0.001), eGFR less than 60 mL/min/1.73 m2 (OR 1.976, p = 0.028), and insulin use (OR 2.257, p = 0.021) were significantly associated with severe hypoglycemia." (PMID 37758787, 2023). "According to the Royal Australian College of General Practitioners (RACGP) guidelines, basal insulin has a lesser risk of hypoglycemia and should be preferred among patients with consistently high fasting blood glucose (FBG) levels." (PMID 36650625, 2023). "In a separate study, it was discovered that severe hypoglycemia was commonly linked to the usage of glimepiride (24.2%) and neutral protamine Hagedorn-insulin and regular insulin “NPH/RI” (38.3%)." (PMID 38169925, 2023). "In this way, it can reduce the risk of hyperinsulinemia, body weight gain caused by systemic insulin treatment, and hypoglycemia." (PMID 37564986, 2023). "Though insulin is associated with the risk of hypoglycemia and weight gain, the addition of vildagliptin or vildagliptin and metformin improved glycemic control with an associated insulin-sparing effect in patients with T2DM." (PMID 38021574, 2023). "MSII has a slow onset of action, yields poor glycemic control, and poses an increased risk of hypoglycemia if the patient is exposed to long-acting insulin when discontinuing PN." (PMID 37674887, 2023). "Decreased α- and β-adrenergic signals result in insulin hypersecretion and the recovery of insulin sensitivity, respectively, after surgical treatment, thereby increasing the risk of hypoglycemia." (PMID 37822367, 2023). "Insulin and epinephrine’s effects on potassium during hypoglycemia can lead to hypokalemia, which is associated with cardiac arrhythmias." (PMID 37887414, 2023). "In a setting of T1D and late-stage (insulin-deficient) T2D, hypoglycemia is the most common complication of intensive glucose-lowering therapy using insulin analogues and/or secretagogues (i.e., sulfonylureas and glinides; T2D only)." (PMID 38298268, 2023). "Our patient's critical sample was consistent with hyperinsulinism, which is a cause of severe hypoglycemia due to increased insulin secretion from the pancreatic beta cells." (PMID 37404330, 2023). "As icodec is a novel basal insulin, the glucodynamics, counterregulation and safety associated with hypoglycaemia require further characterisation." (PMID 37308751, 2023). "Long-acting insulin analogues are suitable in this frail phenotype due to their convenient once-daily administration and low risk of hypoglycaemia due to their less prominent peak levels and long duration of action." (PMID 36837914, 2023). "GLP-1RAs and SGLT2is are both generally well-tolerated when used individually, with a minimal risk of hypoglycemia, unless used in combination with insulin or insulin secretagogues." (PMID 37005640, 2023). "Previous studies have investigated risk factors for hypoglycemia during hospitalization in addition to insulin treatment, although few studies have been specifically focused on patients with T2DM." (PMID 38044455, 2023).
Hypoglycemia (continued). "Randomized controlled trials (RCTs) in adults have demonstrated that insulin degludec is associated with a reduced risk of hypoglycemia than other insulin analogs, at equivalent levels of glycemic control." (PMID 36800034, 2023). "This approach not only restores physiologic insulin secretion but also reduces hypoglycemia risk by partially restoring glucagon secretion." (PMID 36845885, 2023). "The findings of these studies suggest that the amount of additional insulin used for mixed fat and protein meals still needs to be optimized to avoid the risk of postprandial hypoglycemia." (PMID 40303273, 2023). "Last, introducing SGLT2i therapy will allow insulin dose reduction or even insulin cessation and, therefore, hypoglycemia risk." (PMID 36732414, 2023). "As such, when changing to needle-free injectors, the insulin dose should be adjusted in time to avoid increasing the risk of hypoglycemia in patients." (PMID 36864833, 2023). "Selecting the most cost-effective treatments with clinical evidence of lower hypoglycemia risk, especially newer insulin preparations, will have the greatest likelihood of improving clinical outcomes and reducing the economic burden." (PMID 37046876, 2023). "The safety profile of basal insulin analogues is remarkable in terms of reducing hypoglycemia risk, particularly nocturnal hypoglycemia." (PMID 36624650, 2023). "The authors concluded that tirzepatide treatment can achieve better glycaemic control with a lower risk of hypoglycaemia in diabetic patients who are suboptimally controlled with oral glucose-lowering drugs compared to insulin degludec." (PMID 37509514, 2023). "Nevertheless, the associated risk of hypoglycemia episodes limits the flexibility of insulin titration in clinical settings, especially when intensive insulin therapy is necessary." (PMID 37264625, 2023). "Within 24 h of ischemic stroke, glucose potassium insulin (GKI) infusion compared to saline infusion was associated with a higher incidence of asymptomatic hypoglycemia." (PMID 37298308, 2023). "This is partly due to the avoidance of hypoglycaemia-causing medications (e.g. insulin, sulphonylureas) achieved through glucose lowering with an SGLT2 inhibitor in people with T2D." (PMID 37159343, 2023). "Insulin dosage should be carefully adjusted during follow-up due to the risk of hypoglycemia from tapering steroid doses and simultaneous recovery of pancreatic β-cell function." (PMID 37102024, 2023). "Patients receiving insulin had higher glycaemias, strengthening the idea that insulin was certainly used with caution to reduce the risk of hypoglycaemia." (PMID 37330419, 2023). "They arise from pancreatic β cells in the islets of Langerhans and cause hypoglycemia and its symptoms by hypersecretion of insulin." (PMID 38260191, 2023). "High levels of insulin are associated with insulinoma causing the Whipple’s triad (hypoglycemia, low plasma levels of glucose, and resolution of symptoms after correction of the hypoglycemia)." (PMID 37685358, 2023). "Strictly controlling the blood glucose level can delay or prevent the occurrence of T2DM complications, but T2DM patients are susceptible to hypoglycemia during insulin therapy." (PMID 38223574, 2023). "In the present study, the clinical data of 172 T2DM patients undergoing intensive insulin therapy were retrospectively analysed, and the incidence of hypoglycemia after treatment and its risk factors were explored." (PMID 38223574, 2023). "Impaired awareness of hypoglycemia, one of the acquired complications with insulin treatment, can be caused by defective counterregulatory hormone responses to hypoglycemia." (PMID 36769430, 2023). "Tumors producing insulin or IGFs (e.g., Doege–Potter syndrome) are another rare cause of adult-onset hypoglycemia." (PMID 37371827, 2023). "In the second case, high glucose effectiveness would facilitate glucose disposal, predisposing to insulin-independent hypoglycemia." (PMID 37726785, 2023).
Hypoglycemia (continued). "A randomized controlled trial of DPP-4 inhibitors versus insulin secretagogues Which oral antidiabetic drug to combine with metformin to minimize the risk of hypoglycemia when initiating basal insulin?" (PMID 37101024, 2023). "Use of insulin degludec has been associated with reduced risks of hypoglycaemia, particularly nocturnal events." (PMID 36879098, 2023). "Intranasal insulin is also anticipated to offer an increased probability of patient compliance and a lower risk of hypoglycemia than parenteral insulin." (PMID 37511207, 2023). "Rarely, self-administration of insulin causes repeated and unexplained severe hypoglycemia and should be considered a sign of psychological disorders (Factitious hypoglycemia)." (PMID 36769430, 2023). "Increasing evidence suggests these medicines have lower risk of hypoglycaemia than sulphonylureas and insulin, promote weight loss or are weight neutral, and reduce cardiovascular outcomes and mortality in patients at increased cardiovascular risk." (PMID 36662823, 2023). "When a person with AN presents to the ED due to hypoglycemia, they should be admitted because the usual treatments to raise the blood sugar can result in a paradoxical exuberant release of insulin and cause the hypoglycemia to quickly recrudesce." (PMID 36759897, 2023). "According to previous observational studies, the hypoglycemia risk is greater in insulin-treated patients who have been diabetic for a long time and have been on insulin for a long period of time." (PMID 36974247, 2023). "Parents stated that implementing a low CHO diet reduced their child’s need for insulin, making parents feel safer and more in control during the day and reducing the risk of hypoglycaemia at night." (PMID 37049506, 2023). "A small study of 16 pregnant women showed that day-and-night closed-loop insulin delivery was associated with significantly less hypoglycaemia and comparable glucose control compared to SAP therapy." (PMID 37289734, 2023). "One possible cause of hypoglycemia is drugs that cause unregulated exogenous (insulin) or endogenous hyperinsulinemia." (PMID 37633882, 2023). "For example, short-acting insulin and sulfonylureas predispose patients to hypoglycemia, which can increase the risk of falling and, thus, fracture." (PMID 38035029, 2023). "A meta-analysis of seven BEGIN trials showed a lower risk of overall confirmed hypoglycemia in elderly patients with T2DM receiving insulin degludec compared with Gla-100." (PMID 36624650, 2023). "This was attributed to the reduced dosage flexibility and increased risk of hypoglycemia with premixed insulin compared to basal or basal-bolus regimens." (PMID 36650625, 2023). "This combination lowers blood glucose and increases the risk and incidence of hypoglycemia, compared to insulin alone." (PMID 37942482, 2023). "In people who rely on insulin therapy to control their blood sugar levels, episodes of hypoglycemia increase the risk for subsequent episodes of hypoglycemia as part of a vicious cycle." (PMID 37942482, 2023). "Risk of hypoglycemia during and after exercise can be reduced when insulin-dose adjustments are made and/or additional carbohydrates are consumed." (PMID 36593495, 2023). "Hypoglycemia is a frequent acute complication related to inadequate insulin doses, associated oral antidiabetics, deficient caloric intake, progression of renal failure or infectious processes." (PMID 37377235, 2023). "Most PID algorithms also include continuous insulin on board (the amount of insulin still active due to its half-life) to reduce the risk of hypoglycaemia." (PMID 37685946, 2023). "Hypoglycaemia was more common in those with EGI compared to NGT where a delay in early-phase insulin secretion was associated with an increased insulin secretion in the late phase of the OGTT as suggested by a prior report." (PMID 37720541, 2023).
Hypoglycemia (continued). "The risk of hypoglycaemia while on insulin pump therapy is lower than on injection therapy, and on average a better metabolic control is achieved." (PMID 37408713, 2023). "The differential diagnoses of causes of hypoglycemia in the patient were insulinoma, insulin autoimmune syndrome, insulin antagonist hormone depletion, alcohol‐induced hypoglycemia, extra‐pancreatic tumor‐associated hypoglycemia, and reactive hypoglycemia." (PMID 38868726, 2023). "The risk of hypoglycemia during and after exercise can be lowered if specific insulin-dose adjustments are made or by consuming additional carbohydrates." (PMID 37837098, 2023). "Compared to saline-treated mice, modafinil-treated mice adjusted their preference for the food-associated chamber after insulin-induced hypoglycemia." (PMID 37942482, 2023). "These systems use CGM data to adjust insulin delivery in real-time, reducing the risk of hypoglycemia during fasting and keeping blood glucose levels more stable." (PMID 37630716, 2023). "Patients with congenital hyperinsulinism are known to be extremely susceptible to the effects of hypoglycaemia on the brain because insulin also decreases the production of ketones, the alternative fuel for the brain." (PMID 37664849, 2023). "Amongst antihyperglycaemic drugs, insulin and sulfonylureas have the highest potential to cause hypoglycaemia." (PMID 36768000, 2023). "Insulin biosimilars can better simulate the human physiological state of insulin secretion patterns, reduce the risk of hypoglycemia, achieve a more flexible dosing time, improve patient compliance, and reduce diabetic complications." (PMID 37077814, 2023). "Given that insulin is the drug with the greatest risk of hypoglycemia and considering the clinical instability of patients admitted to the hospital, glycemic targets are less strict in hospitalized patients." (PMID 38044455, 2023). "It has been proven that the duration of insulin treatment directly correlates with the risk of hypoglycemia in this population." (PMID 36974247, 2023). "Insufficient food consumption (47%), physical exercise (23%), insulin dose miscalculation (16%), and impaired hypoglycemia awareness (5%) were the most common causes of severe hypoglycemia, according to the findings of the Kedia N study." (PMID 36974247, 2023). "Guidelines developed for managing T2DM in patients during Ramadan recommend basal insulin analogues due to low risk of hypoglycemia than with regular human insulin." (PMID 36624650, 2023). "Ectopic Hk1 expression in β cells accelerates glycolysis in low glucose and causes basal insulin hypersecretion and hypoglycemia similar to that in Lsd1Δβ mice 3 weeks after Lsd1 inactivation." (PMID 36821378, 2023). "The Chinese MERIT study showed that premixed insulin combined with Met resulted in a greater reduction in HbA1c, less insulin consumption, less weight gain, a lower incidence of hypoglycemia, and lower cardiovascular risk than premixed insulin alone." (PMID 38027146, 2023). "It was observed that all doses prevented postprandial hypoglycemia, but also led to important increases in hyperglycemia, probably caused by the strong reduction in the postprandial insulin and GLP-1 response." (PMID 36748934, 2023). "Apart from the need for subcutaneous injection, the two main drawbacks associated with insulin therapy are weight gain and hypoglycemia." (PMID 37373620, 2023). "Hypoglycemic episodes frequently complicate insulin treatment and contrary to hyperglycemia, hypoglycemia can cause irreversible brain damage." (PMID 37511061, 2023). "Insulin is the most efficacious in terms of glucose-lowering potential but can increase weight and is associated with the risk of hypoglycaemia." (PMID 37310947, 2023). "The risk factors of weight gain included using exogenous insulin, intensifying insulin therapy, fear of hypoglycemia and related decrease in physical activity, and psychological factors, such as emotional eating and binge eating." (PMID 37065759, 2023).
Hypoglycemia (continued). "The predominant concern with these agents is the potential for hypoglycemia and this risk seems to be higher with agents like sulfonylureas and glinides that increase or stimulate insulin secretion." (PMID 37120562, 2023). "Among these risk factors, basal insulin dose, blood glucose variability (BG), and past history of hypoglycemic episodes have been identified as the three strongest predictors of iatrogenic hypoglycemia in hospitalized patients." (PMID 37675290, 2023). "History of severe hypoglycemia (OR 5.864, p ≤ 0.001), eGFR less than 60 mL/min/1.73m2 (OR 1.976, p = 0.028), and insulin use (OR 2.257, p = 0.021) were associated with increased risk of severe hypoglycemia." (PMID 37758787, 2023). "As compared with insulin injections, a lower risk of severe hypoglycemia was associated with an insulin pump in the T1D Exchange, the DPV registry and the International Pediatric SWEET Registry." (PMID 36769430, 2023). "Accordingly, retention of endogenous insulin secretion after T1D diagnosis has been associated with better glucose control, lower risk of hypoglycemia, lower insulin requirements, and reduced incidence of retinopathy and nephropathy." (PMID 37249465, 2023). "Our inclusion of insulin analogs reflects changes in prescription patterns observed in older adults, emphasizing the higher risk of severe hypoglycemia and the complexity of managing them in this population." (PMID 37864147, 2023). "In patients with T1D, the risk of hypoglycemia can be reduced by using an insulin pump for insulin delivery instead of multiple daily injections." (PMID 36830610, 2023). "Of the long-acting forms of insulin, degludec has a lower risk of hypoglycemia, possibly due to its longer duration of action and lesser day-to-day variability in absorption." (PMID 36830610, 2023). "IAS also needs to be distinguished from hypoglycemia caused by hypoglycemic drugs or insulin and its analogs." (PMID 36844104, 2023). "As a comparison, oral administration can mimic endogenous insulin distribution with a portal-to-peripheral gradient and ensure normoglycemia with a low risk of hypoglycemia." (PMID 37485249, 2023). "When patients who received insulin or secretagogues during their stay were selected (n = 273), the association between hypoglycemia (i.e., secondary to hypoglycemic treatment) and mortality after admission was still present (P < 0.001)." (PMID 38044455, 2023). "Utilization of intensive insulin regimens and tight glycemic goals are linked to the development of hypoglycemia." (PMID 37120562, 2023). "Since sulfonylureas and isophane insulin are still a major part of treatment in many countries, and since these are associated with higher risk of hypoglycaemia, implementation of TRE among people treated with these drugs should be carefully monitored." (PMID 35684097, 2022). "Analyses were performed to test for associations between dextrose:insulin ratios or method of dextrose administration and the development of hypoglycemia; and for presenting [K+] and mortality." (PMID 36350735, 2022). "Increasing evidence has indicated that cord blood C-peptide was associated with maternal insulin sensitivity, fetal hyperinsulinemia and/or neonatal hypoglycemia." (PMID 36685522, 2022). "The monitoring of plasma glucose is particularly relevant when the treatment includes antihyperglycemic therapies associated with the risk of hypoglycemia, such as insulin or sulfonylureas." (PMID 35329847, 2022). "Insulin is the most adequate therapy for glucose control in severely ill patients, and hypoglycemia risk should be addressed." (PMID 35246230, 2022). "Hypoglycaemia was the main adverse effect within the endocrine system, and this was mainly linked to the use of insulin." (PMID 36243730, 2022). "Although insulin has the greatest glucose-lowering potential of all antihyperglycemic agents, in practice insulin is limited by the risk of hypoglycemia." (PMID 34922811, 2022).